ACAT1 (acetyl-CoA acetyltransferase 1)
Diseases named in the same sentence as ACAT1 in open-access papers (continued):
Sharing a sentence is not in itself a finding about the gene and the disease.
tumor (continued). "Because after ACAT1 is inhibited, the free cholesterol level on the killer T cell membrane increases which makes the T cell tumor antigen immune response more efficient." (PMID 33546704, 2021). "The results indicated that GBM tissues had increased levels of GLDC, SIRT3, and pS6K (a hallmark of mTORC1 activity) and decreased levels of ACAT1, NF-X1, and GLDC K514 acetylation in comparison to non-tumor tissues." (PMID 34244482, 2021). "CE inhibition by the ACAT1 inhibitor avasimibe suppresses tumor growth and restores imatinib sensitivity by downregulating MAPK signaling in imatinib-resistant myeloid leukemia." (PMID 33530546, 2021). "For example, preclinical data showed that inhibition of PCSK9 (proprotein convertase subtilisin/kexin type 9) or ACAT1 (Acetyl-CoA acetyltransferase 1) can improve the anti-tumour effect of the anti-PD-1 antibody in multiple cancers." (PMID 34722305, 2021). "Inhibiting the activity of ACAT1 can greatly improve the anti-tumor function of CD8+ T cells (also known as killer T cells)." (PMID 33546704, 2021). "Inhibition of cell migration and invasion upon ACAT-1 inhibition supports its role in tumor aggression." (PMID 31978092, 2020). "The role of ACAT-1 in tumor cell aggression was studied by blocking ACAT-1 expression/activity in OC-314, SKOV-3 and IGROV-1 cell lines using ACAT-1 specific short hairpin RNA (shRNA)." (PMID 31978092, 2020). "Inhibiting ACAT-1 and depleting CE levels seems to have an anti-tumor effect in terms of regulation of apoptosis, cell proliferation, migration and invasion properties in addition to enhancing the sensitivity to cisplatin." (PMID 31978092, 2020). "The anti-tumor effects observed upon ACAT-1 inhibition can be attributed to enhanced apoptosis as confirmed by elevated caspases and reduced mitochondrial membrane potential." (PMID 31978092, 2020). "Yet, though CEs serve as a cholesterol reservoir, the accumulation of CEs or overexpression of ACAT1 have supported a pro-tumor role." (PMID 32486083, 2020). "Above all, the discovery of drugs that can both enhance anti-tumor immunity and directly kill tumors, such as imatinib and ACAT-1 inhibitors, is the focus of future drug development." (PMID 31519198, 2019). "In mice treatment of ACAT-1 inhibitor notably suppressed tumor growth and extended the length of survival time." (PMID 29793481, 2018). "Pharmacological or genetic ACAT1 inhibition attenuates cancer cell proliferation and invasive activity in vitro and tumor growth and metastasis in xenograft models." (PMID 30283400, 2018). "In a mouse model of pancreatic cancer, depletion of ACAT1 suppressed tumour growth and metastasis by increasing intracellular free cholesterol levels, causing elevated ER stress and cell death." (PMID 30081476, 2018). "Ex vivo measurement of tumor volume and weight confirmed the tumor suppressing effect of ACAT-1 knockdown." (PMID 27132508, 2016). "After 5 weeks of tumor cell inoculation, the ACAT-1 knockdown cells developed significantly smaller tumors compared with the ACAT-1 wild-type cells." (PMID 27132508, 2016). "ACAT1 may serve as an excellent adjuvant for DC vaccines to help them better exert their anti-tumor effects." (PMID 40491907, 2025). "Previous studies have revealed the role of ACAT1 in controlling tumor growth." (PMID 40166937, 2025). "Considering that NK cells in the TME have been reported to exhibit different phenotypes, including dysfunctional states, we examined NK cells isolated from orthotopic tumors and performed Smart-seq2 to ensure that the elevated tumor-infiltrating NK cells induced by ACAT1 were activated." (PMID 40289129, 2025).
tumor (continued). "Astonishingly, tumor growth was appreciably decreased and the proportions of tumor-infiltrating NK cells as well as cytotoxic NK cells were dramatically increased after disruption of the mitochondrial location of ACAT1." (PMID 40289129, 2025). "Considering that the level of nuclear ACAT1 is higher in peritumoral tissues than in CRC tumor tissues, we hypothesized that a benign immune microenvironment might facilitate ACAT1 nuclear localization." (PMID 40289129, 2025). "Conversely, OXCT1 and ACAT1 expression levels were decreased in INSS stage 4 tumours, when compared to stage 1 in all datasets, indicating the potential reduced reliance of metastatic NB on rate‐limiting ketolytic enzymes under nutrient stress, while BDH1 levels were unchanged." (PMID 41420301, 2025). "We next examined the effects of ACAT1 in GC cells on tumor angiogenesis." (PMID 41184227, 2025). "In that study, ACAT1-mediated acetylation of these components inhibited the complex activity, promoting glycolysis over glucose oxidation and thus functionally supporting tumor cell proliferation." (PMID 39841826, 2025). "Moreover, the level of nuclear ACAT1 was positively correlated with NK cell infiltration in tumor tissues from CRC patients, implying an advantage of nuclear ACAT1 in NK cells recruitment." (PMID 40289129, 2025). "Notably, the authors found that ACAT1-dependent tumor cell–derived reactive oxygen species (ROS) limited B cell viability and reduced TLS formation." (PMID 40166937, 2025). "Combined with its well-established cell-autonomous role in driving tumor cell proliferation, the enzyme ACAT1 could fuel dual mechanisms to promote cancer." (PMID 40166937, 2025). "The nuclear ACAT1 level in peritumoral tissues is relatively higher compared to tumor tissues, suggesting that multiple kinases may regulate ACAT1 pS60." (PMID 40289129, 2025). "Therefore, DC vaccines can be combined with ACAT1 inhibitor therapy to simultaneously enhance CD8+ T cell-mediated anti-tumor immune responses through both mechanisms." (PMID 40491907, 2025). "Studies have shown that ACAT1 also has acetyltransferase activity, specifically acetylating PDH, reducing its enzymatic activity, increasing pyruvate levels and promoting lactate production and tumour growth through the Warburg effect, making ACAT1 a potential new anti‐cancer target." (PMID 39778006, 2025). "Importantly, inducible knockdown of tumor cell Acat1 in established KP tumors showed similar results, suggesting the therapeutic potential of targeting Acat1." (PMID 40166937, 2025). "Combination treatment of ACAT1 inhibitor and sorafenib could significantly inhibit tumor growth in HCC xenografts, indicating that pharmaceutical inhibition of ACAT1 could be a promising target in anti-HCC strategy." (PMID 38720812, 2024). "Herein, a comprehensive understanding of the role of ACAT1 in tumor development and anti-tumor immunity may provide new insights for anti-tumor strategies." (PMID 38720812, 2024). "Further assessment of subcutaneous tumor tissues from nude mice revealed decreased expression of the cell proliferation marker Ki67 in the ACAT1 stable knockdown group, confirming the role of ACAT1 as an oncogene in BLCA development." (PMID 38817856, 2024). "Modifying the activity of ACAT1 might be a feasible method to modulate the anti‐tumor efficiency of killer T cells." (PMID 39323079, 2024). "ACAT1-deleted CD8+ T cells exhibited impaired tumor growth and metastasis of melanoma." (PMID 38720812, 2024). "ACAT1, as a metabolic enzyme, is involved in tumor progression." (PMID 39494339, 2024). "Moreover, due to the important role of cholesterol metabolism in immune function, ACAT1 is also essential for regulating anti-tumor immunity." (PMID 38720812, 2024). "The enhanced activation and cytokine release in shACAT1-19CAR-T cells might be due to the modulation of membrane properties and increased responsiveness of T cells to tumor antigens as a result of ACAT1 knockdown." (PMID 38534399, 2024).
tumor (continued). "ACAT1 inhibition may be exploited as a potential strategy to enhance the anti-tumor immunity and eliminate tumors." (PMID 38720812, 2024). "In addition, acetyl-coA acetyltransferase 1(ACAT1) is a fatty acid metabolizing enzyme, and Tyr407 phosphorylation of ACAT1 promotes the stability of its tetramer morphology and accelerates tumor metabolism." (PMID 39366930, 2024). "A chi-square test analyzing the association between ACAT1 mRNA expression and the clinicopathological features of BLCA patients in the TCGA database indicated that ACAT1 mRNA expression levels were positively related to tumor grade, stage, and M stage." (PMID 38817856, 2024). "Targeting tetrameric ACAT1 has been proposed as a promising anti-tumor strategy." (PMID 38720812, 2024). "Insulin-induced tumor progression of CRC is regulated by ACAT1." (PMID 38720812, 2024). "Suppression of acetyl-CoA acetyltransferase 1 (ACAT1) responsible for cholesterol esterification or cholesterol transporter proprotein convertase subtilisin/kexin type 9 (PCSK9) improves the anti-tumor performance of CD8+ T cells and potentiates ICB therapy." (PMID 38362156, 2024). "The PC level in the tumor issues of ACAT1 KD animal group was also increased significantly." (PMID 39494339, 2024). "Recent studies introduced the complex role of ACAT1 in tumor development and anti-tumor immunity, which may provide new insights for anti-tumor strategies." (PMID 38720812, 2024). "Targeting ACAT1 has been identified as a potential anti-tumor strategy." (PMID 38720812, 2024). "Small molecule inhibitors that target ACAT1-mediated ME1 acetylation may be a potential anti-tumor strategy for CRC patients." (PMID 38720812, 2024). "ACAT1 inhibition could impair cholesterol esterification, therefore potentiating anti-tumor effect and strengthening cell proliferation of CD8+ T cells." (PMID 38720812, 2024). "The impact of ACAT1 inhibition extends to melanoma, where Avasimibe enhances the cytotoxic response from T cells in mouse models, concurrently resulting in a decrease in metastatic dissemination and tumour growth." (PMID 38610991, 2024). "We then wanted to evaluate whether the percentages of ACAT1 positively stained cells and ACAT1 total score staining were similar or different between tumour and their adjacent pre-tumour matched tissues in our 21 patients." (PMID 36816175, 2023). "Indeed, treatment of breast cancer cells with ACAT-1 inhibitors resulted in reduced cell proliferation and migration and reduced tumor growth through regulation of cholesterol metabolism." (PMID 37089950, 2023). "The expression of ACAT1 in OSCC tumours is heterogeneous between patients." (PMID 36816175, 2023). "In glioblastomas, inhibition of ACAT1 inhibits adipogenesis and tumor growth." (PMID 37089950, 2023). "Moreover, we have identified HMGCR and ACAT1 expression in the tumor region as possible markers for tumor progression and ABCA1 as anti-cancer gene in LUAD." (PMID 37024569, 2023). "Indeed, out of the 21 patients, high ACAT1 protein expression was found in the pre-tumour tissue of 6 patients (29%) and low ACAT1 protein expression in 15 patients (71%)." (PMID 36816175, 2023). "Variable ACAT1 protein expression was observed in pre-tumour tissues, similar to OSCC tissues." (PMID 36816175, 2023). "Building on the idea that allocating cholesterol towards cellular membranes in CD8+ T cells is beneficial for the anti-tumor response, researchers found that pharmacologic inhibition of ACAT1 in combination with anti-PD-1 treatment synergistically reduced the growth of mouse melanoma tumors." (PMID 37842241, 2023). "In order to determine whether peritoneal fluid and plasma ACAT1 levels can predict tumor ACAT1 status, we assessed the correlation between tissue, peritoneal fluid and plasma ACAT1 protein levels." (PMID 35399074, 2022).
tumor (continued). "The fact that ACAT1 expression was absent or minimal in benign masses and normal tissues and significantly higher in EOC samples indicates the importance of ACAT1 in EOC development; therefore, ACAT1 could be a potential tumor specific target." (PMID 35399074, 2022). "Moreover, ACAT1 protein levels in EOC tumor tissue were significantly higher compared to pelvic masses (n = 7; p = 0.0002) and normal ovaries (n = 19; p = 0.0085) separately." (PMID 35399074, 2022). "Indeed, ACAT1 inhibition in B16 melanoma-bearing mice promoted CD8 T cell tumor infiltration while enhancing effector function and proliferation in vivo." (PMID 34983949, 2022). "Decreased ACAT1 activity leads to impaired cancer cell proliferation and tumor growth." (PMID 35053570, 2022). "Targeting ACAT1 to prevent cholesterol ester formation may impair tumor growth while promoting the production of cytokines and cytolytic granules by CD8 T cells." (PMID 34983949, 2022). "ACAT1 is also important for cancer cell proliferation and tumor growth." (PMID 35178152, 2022). "ACAT1 mediated accumulation of CE may alter cell signaling to promote tumor proliferation and survival." (PMID 35399074, 2022). "This may imply that tissue ACAT1 mediates secretion of CE into peritoneal fluid; therefore assessment of CE from peritoneal fluid may be indicative ACAT1 levels in tissue and tumor aggressiveness." (PMID 35399074, 2022). "Moreover, dual therapy with an ACAT1 inhibitor and anti-PD-1 agent was better than either therapy alone at inhibiting tumor progression in vivo." (PMID 34983949, 2022). "At the same time, ACAT1 was always present in the cytoplasm of tumor cells." (PMID 36517760, 2022). "The inhibition of cholesterol esterification by the enzyme cholesterol acyltransferase 1 (ACAT1) utilising the repurposed drug avasimibe leads to an improved anti-tumour response by CD8+ T cells that further enhanced outcomes in combination therapy with anti-PD-1 treatment." (PMID 33925949, 2021). "ACAT1 inhibitors like Avasimibe are already approved for clinical use and have shown improved outcomes in combination therapy with checkpoint inhibitors in tumour mouse models." (PMID 34086048, 2021). "The complicated energetics in tumor may be the cause of these contradictory results and it seems that the anti-tumor effect of ACAT1 needs to be further investigated." (PMID 33865459, 2021). "Finally, ACAT1 inhibitor or shRNA knockdown significantly suppressed tumor growth and metastasis in an orthotopic mouse model of pancreatic cancer." (PMID 34638609, 2021). "In addition, it was shown that inhibition of ACAT1 in combination therapy with anti-PD-1 antibodies improved efficacy in controlling tumour progression." (PMID 34202553, 2021). "Meanwhile, the inhibition of ACAT1 strengthens the tumor-limiting activities of CD19-CAR-T cells by elevating the ratio of effector-to-target cells even under low infection rates and could rescue CD8+ T cell inhibition in chemo-immunotherapy." (PMID 34742349, 2021). "Restoring its expression significantly reduced the malignant behavior of ccRCC cells in vitro, suggesting that ACAT1 might be a tumor suppressor." (PMID 34485115, 2021). "ACAT1 plays a tumor-promoting role in pancreatic cancer and lymphocytic leukemia." (PMID 33530546, 2021). "Publications about the dysregulation of ACAT1 and its role in tumor pathogenesis are rare." (PMID 34485115, 2021). "In summary, ACAT1 may function as a tumor suppressor via modulation of ketogenesis and could thus serve as a potential therapeutic target in NPC." (PMID 34485115, 2021). "In triple-negative breast cancer, the inhibition of ACAT1 expression could reduce tumor growth in TNBC mammospheres." (PMID 34638609, 2021). "The decreased ACTA1 in late-stage HCC may be caused by metabolic changes, and a number of results showed that over-expression of ACAT1 inhibited the proliferation and migration of tumor cells." (PMID 33865459, 2021).
tumor (continued). "In xenograft models of glioblastoma, ACAT1 ablation has reduced the tumor progression." (PMID 32486083, 2020). "To evaluate whether ACAT-1 inhibition affects tumor aggressiveness, we measured cell invasion and migration abilities of ACAT-1 inhibited and control cell lines." (PMID 31978092, 2020). "Therefore, the ACAT1 inhibitor avasimibe enhances the proliferation and effector function of CD8 T cells and ACAT1-deficient CD8 T cells performed better in controlling tumor growth." (PMID 33120978, 2020). "Inhibiting ACAT1 further improved anti-tumor efficacy of anti-PD1 antibody." (PMID 30283400, 2018). "Tumor growth was dramatically suppressed with ACAT-1 knockdown while no obvious loss in body weight was observed." (PMID 27132508, 2016). "Consequently, ACAT1 inhibitors have been designed to inhibit tumor growth and metastasis." (PMID 39857793, 2025). "However, the role of ACAT1 in the tumor microenvironment (TME) is unclear." (PMID 40166937, 2025). "Thus, ACAT1 has the potential to be a therapeutic target in anti-tumor therapy." (PMID 38169575, 2024). "It has been reported that ACAT1 exists in the form of a tetramer, in which the Y407 site of ACAT1 can make the tetramer more stable and enhance its activity while damaging the stability of the ACAT1 tetramer, and the knockdown of ACAT1 can effectively control tumor growth." (PMID 37375824, 2023). "These variable expression levels of ACAT1 in OSCC tumours could be explained by several hypotheses." (PMID 36816175, 2023). "Therefore, ACAT1 can be used as a marker to predict tumor immune response to a certain extent." (PMID 37064872, 2023). "Thus, if one inhibits the influx of BHB with compounds such as Syringopine or Syrosingopine from Rauwolfia or others such as Quercetin or Epigallocatechin tumor cells will starve, since ketolysis should decline, particularly if associated with SCOT and ACAT1 inhibitors." (PMID 36836124, 2023). "Thus, inhibiting SCOT the specific ketolytic enzyme and ACAT1 should hold back tumor progression." (PMID 36836124, 2023). "Avasimibe, an inhibitor of the cholesterol esterification enzyme ACAT1, increases cholesterol levels in the cell membrane, facilitating the formation of immune synapses and signal transduction, resulting in superior anti-tumor efficacy in different mouse models." (PMID 36231064, 2022). "Indeed, our study decoded ACAT1 and CE as important components of the tumor microenvironment which may contribute to cancer aggressiveness and drug resistance." (PMID 35399074, 2022). "Similarly, down-regulating ACAT1 expression or avasimibe administration could efficiently inhibit the growth and metastasis of Lewis lung carcinoma via potentiating the anti-tumor response of CD8+ T cells." (PMID 34638609, 2021). "Increasing ACAT1 induces CE accumulation and may promote tumor proliferation." (PMID 34066761, 2021). "Therefore, ACAT1 appears to increase the tumor-promoting function of CAV1, by favoring LDL uptake, as reported in endothelial cells, and also the formation and stabilization of lipid droplets, which aid in sustaining tumor cell proliferation under adverse conditions." (PMID 32458269, 2020). "Importantly, this natural product, arecoline, showed anti-tumor activity, further validating that drugs targeting ACAT1 might be valuable as anti-cancer agents." (PMID 29108233, 2017). "TRIM8 and its induced K63 ubiquitination promote the interaction of PGK1 with ACAT1, thereby facilitating PGK1 acetylation and downstream glycolysis for lactate accumulation and tumor angiogenesis." (PMID 41184227, 2025).